MMP9 (matrix metallopeptidase 9)
Diseases named in the same sentence as MMP9 in open-access papers (continued):
Sharing a sentence is not in itself a finding about the gene and the disease.
cancer (continued). "Prior research has also demonstrated that increased MMP-9 expression resulted in a poor prognosis in a variety of cancers." (PMID 28624794, 2017). "It is well known that MMPs play a crucial role in the invasion, migration and angiogenesis of cancer cells and that MMP-9 is a major factor in cancer cell migration and invasion." (PMID 28424406, 2017). "The fact that low-risk cancers showed lower Ktrans and Kep values was consistent with their less MVD and lower VEGF-1, MMP-2, and MMP-9 expression levels." (PMID 29371992, 2017). "In the process of cancer metastasis, MMP-9, CD44v6 and vimentin are responsible for cell migration, invasion and cell-matrix adhesion." (PMID 28774312, 2017). "SM22 can act as a cancer repressor by modulating the secretion of matrix metalloproteinase 9 (MMP9) or the AR signaling pathway." (PMID 29029391, 2017). "Expression of both Matrix Metalloproteinase 2 (MMP2) and Matrix Metalloproteinase 9 (MMP9) was higher in cancer microtissues than in fibroblast-free microtissues." (PMID 29112150, 2017). "HMGB1 has been reported to mediate MMP2 and MMP9 expression in some inflammatory disorders and cancers." (PMID 28348451, 2017). "Among all the involved proteases, MMP2 and MMP9 are the most essential for degradation of the basement membrane and so they play a major role in cancer invasion and migratio." (PMID 28881668, 2017). "Our study demonstrates, for the first time, how Ganoderma lucidum extracts can significantly inhibit the release of IL-8, IL-6, MMP-2 and MMP-9 in cancer cells under pro-inflammatory condition." (PMID 28264501, 2017). "Specifically, the activities of gelatinases MMP-2 and MMP-9 correlate with the invasive potential of cancer." (PMID 29152067, 2017). "Matrix metalloprotein-9 (MMP-9) acts as an important oncogene that promotes cancer cell migration and migration and mediates extracellular matrix (ECM) degradation." (PMID 28624794, 2017). "Matrix metalloproteinase MMP2 and MMP9 are well known for their role in cell migration and invasion of cancer cells." (PMID 28212565, 2017). "We next examined the expression of MMP-2 and MMP-9, which are widely known as critical molecules involved in cancer invasion and metastasis." (PMID 28548944, 2017). "Previous studies have demonstrated that transcription factors including Sp-1, AP-1, and NF-κB play​​ a key role in the regulation of MMP-9 in cancers." (PMID 28680385, 2017). "Together with MMP-9, which is frequently up-regulated in cancer cells and in adjacent host tissues, it is involved in the invasion and metastasis of cancer cells." (PMID 29271940, 2017). "In very recent years protective functions of MMP9 have also been described in other cancers/malignancies." (PMID 27861153, 2017). "MMP-9 has been proved to facilitate the invasion capacity of cancer cells by damaging the histological barrier around the extracellular matrix." (PMID 29221199, 2017). "It is well known that MMP‐2 and MMP‐9 are overexpressed and promote cancer cell invasion and metastasis in many cancers." (PMID 28846829, 2017). "Regarding SCLC a dramatic reduction of EGF, CAL and MMP-9 levels in limited SCLC prevents the distinction from non-cancer patients." (PMID 28117344, 2017). "Inhibition of MMP-2 and MMP-9 expression and activity in cancer cells has been shown to prevent their migration and invasion." (PMID 28481901, 2017). "Isothiocyanates, particularly PEITC, suppressed 12-O-tetradecanoylphorbol-13-acetate (TPA)-induced MMP-9 activity and invasion in various cancer cell lines." (PMID 28969043, 2017). "Mere15, novel polypeptide, suppressed the expression of MMP-2 and MMP-9 and eventually inhibits cancer cell metastasis." (PMID 29233192, 2017). "LncRNA HOTAIR enhances cancer cell invasion and metastasis by up-regulating matrix metallopeptidase 9 and vascular endothelial growth factor." (PMID 29228655, 2017).
cancer (continued). "FOXP4, a member of the FOXP subfamily, can enhance cancer proliferation and migration by targeting matrix metalloproteinase-9 (MMP9), thus acting as an oncogene." (PMID 28272374, 2017). "Western blotting of B16shR-SOCS1 total cell lysate showed decreased expression of MMP2, MMP9 and CD10, implicated in malignant tumor progression, as compared with B16F10-Nex2 total cell lysate." (PMID 28079159, 2017). "In particular, MMP-2 and MMP-9 are known to degrade type IV collagen, which is the major component of the basement membrane, and induce cancer progression and metastasis." (PMID 28481901, 2017). "Suppression of any of these components has been reported to decrease the expression of MMP-9/2 and potentially prevent cancer cell migration and invasion." (PMID 28729634, 2017). "Taken together, we provide a comprehensive in vitro analysis of MMP-2 and MMP-9 activity in Rb in several checkpoints that are deregulated in cancer." (PMID 28633655, 2017). "CXCL1, MMP9, IL1B, WNT7A, and CCL2 were associated with cancer malignant characteristics which were remarkably decreased in Top 10 list." (PMID 28881805, 2017). "The mRNA levels of cancer-related genes including β-catenin, E-cadherin, Mmp2 and Mmp9 were higher in CK8+/− mice than in WT mice." (PMID 29228570, 2017). "The effect of NO· free radical and MMP-9 on the inflammation and cancer, as well as the interaction between NO· free radical and MMP-9 have been well known." (PMID 28969037, 2017). "Specifically, MMP-2 and MMP-9 are the most-studied MMPs in the context of cancer, including metastasis." (PMID 28507454, 2017). "Type IV collagenase matrix metalloproteinases (MMPs), in particular, MMP-2 and MMP-9 and gelatinase A and gelatinase B, respectively, have been found to promote invasion and metastasis of malignant tumors." (PMID 29181405, 2017). "As matrix metalloproteinase-7 (MMP7), MMP9 and E-cadherin are known to be involved in cell migration and invasion in some human cancers, we examined their expression under these conditions." (PMID 27863429, 2017). "Cancer Clinical Trials with an anti-MMP-9 therapeutic antibody were recently initiated, prompting us to investigate the role of MMP-2, −9 in Rb metastasis." (PMID 28633655, 2017). "Since MMP-9 resulted the marker that better discriminated cancer from controls, this molecule was combined with MMP-1 and/or -7 with the intention of increasing its diagnostic performance." (PMID 29207990, 2017). "FAK also regulates phosphorylation of ERK and Akt, and the FAK-ERK and FAK-Akt signaling pathway induces MMP-9 expression in several cancer cell lines." (PMID 28969043, 2017). "Degradation of extracellular matrix and vascular basement membrane is required for a cancer cell to invade and form metastasis and it is known that matrix metalloproteinases, in particular MMP9, are essential for invasion of TNBC cells." (PMID 29158506, 2017). "A large number of literature studies shown that VEGF, MMP-2 and MMP-9 have been regarded as metastasis-related genes, which play important roles in cancer invasion and metastasis." (PMID 29156710, 2017). "In part, this is due to MMP-9-mediated degradation of extracellular matrix, facilitating influx of leukocytes into inflamed tissues and invasion or metastasis of cancer cells." (PMID 28369077, 2017). "Array signal intensity value for MMP9 in Gleason 4 cancer cells was 3004.10, ~12-fold higher than that of 238.41 in Gleason 3 cancer cells." (PMID 29254211, 2017). "We also found that miR-200b-3p and miR-429-5p dually inhibited expression of PCNA, MMP2, and MMP9, protein biomarkers of cancer-cell proliferation and motility, in MDA-MB-231 and HCC1937 cells." (PMID 29156719, 2017). "Specifically, MMP-2 and MMP-9 inhibitor, termed 5a, has been proven to enhance apoptosis in cancer cells." (PMID 28746469, 2017).
cancer (continued). "Although MMP-9 has been demonstrated to play a central role in cancer metastasis, we found that the propoxur-induced MCF-7 cell migration was not mediated by MMP-9 protein." (PMID 29152067, 2017). "In a considerable set of recent publications, two antibiotics (minocycline and azythromycin) and the proteasome inhibitor bortezomib, used in cancers, were reported to inhibit MMP-9 at different stages of its expression, activation or activity." (PMID 28369077, 2017). "Of the MMPs, a specific subset are the gelatinases (MMP-2 and MMP-9), which have been the subject of research for their high levels of expression in various malignant tumors and close relation with cancer cell metastasis." (PMID 28350337, 2017). "Among the MMPs, MMP-2 and MMP-9 are the gelatinases expressed in cancer cells, and their proteolytic activity contributes to metastasis." (PMID 28481901, 2017). "For example, the STAT3 transcription factor induces the expression of matrix metalloproteinase 2 (MMP-2), MMP-9, and epithelial–mesenchymal transition-related genes in promoting cancer cell invasion and metastasis." (PMID 28856117, 2017). "Activated Akt/NF-κB signaling pathway increased the expression of downstream proteins, such as MMP2 and MMP9, and finally result in cancer cell migration, invasion and metastasis." (PMID 29088737, 2017). "Surfactin inhibits cancer metastasis by downregulating MMP-9 expression that is mediated by NF-κB, AP-1, PI3K/Akt, and ERK1/2 inactivation." (PMID 29123482, 2017). "MMP-2 and MMP-9 can degrade matrix collagen and basement membrane and correlate with the invasive and metastatic properties of cancer." (PMID 28678918, 2017). "TNF-α can also induce the expression of many oncoproteins through NF-κB or p38 signaling, such as JAG1, Fascin, VEGF and MMP2/MMP9, to promote the development of cancers." (PMID 28938560, 2017). "Our study indicates that, fibroblasts act upon carcinoma cells to increase the expression of pro-angiogenic factors such as MMP9." (PMID 28423685, 2017). "Exploring the mechanism of MMP9 regulation by cytokine crosstalk in carcinoma cell lines, we found that this response requires TAK1 and both IKK kinases, as well as RELA/p65, a subunit of the canonical NF-κB transcription factor." (PMID 28423685, 2017). "We explored the mechanism of MMP9 regulation in direct co-cultures of carcinoma cells and fibroblasts." (PMID 28423685, 2017). "Previous studies have shown that MMP-2 and MMP-9 play a critical role in cancer cell invasion by stimulating the degradation of the ECM31." (PMID 27251589, 2016). "Another active ingredient of green tea, EC, can down-regulate MMP-9 expression explaining the inhibitory effect of EC on invasion of cancer cells into embryonic stem cell-derived, vascularized tissues." (PMID 27999314, 2016). "Upregulations of MMP2, MMP7, and MMP9 have been mostly reported as enhancements to the migratory and invasive ability of cancer cells." (PMID 26701209, 2016). "MMP-9 is part of the MMPs family and is the most important component in cancer tissue remodeling, able to catalyze types V, VII, IX, X, and IV collagen, elastin, fibrin, fibrinogen and plasminogen to facilitate malignant cell invasion and metastasis." (PMID 26918342, 2016). "The role of MMPs in cancer development, and specifically the role of MMP9, has been well documented." (PMID 27029067, 2016). "In this regard, oncogenic RAS-mediated upregulation of MMP2, MMP9, and cathepsin B has been shown to be particularly important in stimulating cancer cell proteolytic activity and invasion." (PMID 27351226, 2016). "Emerging evidences have suggested that Notch1 induces increase of MMP-2 and MMP-9 expression that were important in cancer invasion and the extracellular matrix remolding during VM development." (PMID 27793002, 2016). "Class I HDACs, HDAC 1 and HDAC 2, have been shown to increase invasion through the upregulation of MMP-2 and MMP-9 in different cancer cell lines." (PMID 27506904, 2016).
cancer (continued). "Overexpression of MMP-2 and MMP-9 promotes cancer progression and is highly correlated with poor prognosis of cancer patients." (PMID 27733866, 2016). "It has been reported that Akt promotes cancer cell invasion by increasing matrix metallopeptidase (MMP-9)." (PMID 26882563, 2016). "Activation of MMPs, in particular MMP-2 and MMP-9, plays crucial roles in tissue matrix degradation, and thus, paves the way for cancer cell migration." (PMID 26760964, 2016). "TNF-α is considered to be one of the strongest physiological inducers of MMP9 expression, the enzyme which appears necessary for sustained migration of various cell types, including cancer cells." (PMID 27042827, 2016). "Of the MMPs, MMP-2 and MMP-9, known as the gelatinases that degrade the main constituent of the basement membrane and type IV collagen, have been recognised as crucial in cancer invasion and metastasis." (PMID 26980735, 2016). "Serum MMP-9 showed almost similar ability to diagnose cancer in healthy subjects (YI: 0.17; overall accuracy: 58.1%)." (PMID 27811960, 2016). "Under certain conditions, MMP9 degrades these collagens, thereby expediting and facilitating cancer cell invasion and metastasis." (PMID 27777384, 2016). "CK19 mRNA and MMP-9 were significantly more often expressed in patients with G2 and G3 cancers (p < 0.01) in comparison with G1 tumors." (PMID 27110764, 2016). "The levels of endothelial cell marker VE-cadherin, MMP-2 and MMP-9 expression in CD133+ cancer stem-like cells and xenograft tumors of nude mice injected with CD133+ cells were significantly higher than those with CD133− cells." (PMID 27074560, 2016). "Evolving evidences implicate that STAT3 activation is involved in MMP-9 expression and matrix remodeling and thus confers enhanced invasion ability in drug-resistant cancer cells." (PMID 27793010, 2016). "Proteolytic enzymes, such as MMP-9, were required for invasion processes to degrade extracellular matrix, thereby facilitating the invasion of cancer cells to surrounding tissues." (PMID 27793010, 2016). "We propose here a graphical abstract illustrating that the Snail-MMP9 signaling axis maintains several important cancer growth factor receptor signaling platforms in promoting Neu1-MMP9 crosstalk in complex with glycosylated receptors." (PMID 27029067, 2016). "Exposure to 20 mg/kg picetannol significantly reduced the number and volume of pulmonary cancer nodules and expression of MMP-9 in both lung and cancer in nude mice." (PMID 27999314, 2016). "Extracellular matrix-degrading MMPs, especially MMP-2 and MMP-9, are involved in the metastasis of cancer cells." (PMID 27733866, 2016). "Intriguingly, moderate levels of membrane type 1-MMP and MMP-9 were detected in cancer and stromal cells." (PMID 27175590, 2016). "The MMP-9 expression was significantly increased in cancer tissue compared with that in the normal parts in HNSCC." (PMID 26980735, 2016). "BQ components further activated matrix metalloproteinase-2 (MMP-2) and MMP-9 in oral epithelial cells and cancer cells, contributing to the invasion and metastasis of OSCC." (PMID 26919242, 2016). "This is the first study that identifies a new Rab40b–Tks5- and miR-204-dependent invadopodia transport pathway that regulates MMP2 and MMP9 secretion, and extracellular matrix remodeling during cancer progression." (PMID 27789576, 2016). "The potential roles of MMP9 include the regulation of cancer progression, activation of angiogenesis, and recruitment of macrophages or other bone marrow–derived myeloid cells to the pre-existing metastatic niche." (PMID 27765919, 2016). "Many studies have been conducted on the relationship between uPA as well as MMP9 expression in cancer patients." (PMID 26906973, 2016). "The role of MMP-2 and MMP-9 in metastasis is to degrade proteins in the extracellular matrix, and eventually affect cancer progression and invasion." (PMID 27618887, 2016).
cancer (continued). "MMP-9 disrupts the basement barrier and promotes the migration of capillary endothelial cells to initiate cancer angiogenesis." (PMID 27153056, 2016). "A number of previous studies showed an increase in the expressions of MMP-2 and MMP-9 within various malignancies, and these enzymes were proposed as potential cancer markers." (PMID 27406386, 2016). "MMP (matrix metalloprotein) family play an important role in invasion and metastasis of cancer cells; therefore, the expression of MMP9 between control and AQP9-siRNA were conducted." (PMID 27187384, 2016). "MMP-2 and MMP-9 are important members of soluble MMPs and play important roles in cancer development." (PMID 27618887, 2016). "On the one hand, this iron regulatory protein can bind to matrix metalloproteinase-9 (MMP-9) to form MMP-9/NGAL complex, protecting MMP-9 from proteolytic degradation commonly associated with the clinical progression of human cancers." (PMID 27863382, 2016). "AP-1 signaling was reported to regulate cyclin D1, cyclin E and MMP9 in various cancers including NSCLC." (PMID 27184257, 2016). "S100A8 and S100A9 knockdown significantly decreased MMP2 and MMP9 protein levels in the cancer cells." (PMID 27086923, 2016). "Overall, honey constituents are shown to lower the expression of MMP-2 and MMP-9 in a range of cancer cell lines, however, currently there is limited evidence on the effect of honey on the metastatic properties of cancer." (PMID 28933410, 2016). "A number of studies have proposed that the activation of p38 MAPK contributes to EMT and the overexpression of MMP9 in many tumors, offering cancer cells enhanced invasion and migration capabilities." (PMID 27806310, 2016). "Downregulation of S100A8 and S100A9 was further accompanied by decreased MMP2 and MMP9 expression in cancer cells, both in culture and in metastatic liver colonies." (PMID 27086923, 2016). "It has been reported that MMP9 can be induced by the interaction between macrophages and cancer cells." (PMID 27487154, 2016). "Both PTEN and PDCD4 were identified as the upstream suppressors of matrix metallopeptidase 9 (MMP-9) which facilitated cancer cell migration through degrading the collagenous substrates in the surrounding extracellular matrix." (PMID 27533461, 2016). "Integrin-binding sialoprotein (IBSP), another osteomimicry marker, and matrix metalloprotease 9 (MMP9), a marker of cancer cell aggressiveness expressed by osteoclasts in bone tissue, were also overexpressed in the BM primary culture." (PMID 27556456, 2016). "This study is the first to demonstrate that macrophage AEG-1 not only induced MMP-9 expression in macrophages but also up-regulated MMP-9 expression in cancer cells." (PMID 27793010, 2016). "This highlights MMP9 as a potential target for further intervention at least in the subset of cancers carrying SMAD4 HD." (PMID 27655713, 2016). "MMP2 and MMP-9 also contribute to BQ-related oral carcinogenesis by promotion of cancer invasion and metastasis." (PMID 26919242, 2016). "It has been shown that constitutive activation of STAT3 induces proliferation and invasion of cancer cells via activation of several downstream target genes such as c-Myc and MMP9." (PMID 27824155, 2016). "MMP9 is particularly interesting, since a basic level of expression in most cells is generally low, whereas it is highly expressed in most human cancers and responds to growth factors and cytokines." (PMID 27110571, 2016). "The review performed by Abba M and colleagues, comprising data from 55 different studies, showed a group of 13 miRNAs that target the matrix metalloproteinases (MMPs) MMP-2 and MMP-9 in a large variety of cancers types." (PMID 27187371, 2016). "Activating the MAPK pathway is crucial for inducting MMP-9 expression in various cancer cell lines, and suppressing the MAPK signalling pathway can reduce MMP expression." (PMID 26980735, 2016).